IGF2 (insulin like growth factor 2)
Diseases named in the same sentence as IGF2 in open-access papers (continued):
Sharing a sentence is not in itself a finding about the gene and the disease.
Wilms tumor (90 papers, 2000 to 2025). An embryonal neoplasm characterized by the presence of epithelial, mesenchymal, and blastema components. "Misregulation of the imprinted IGF2 results in Beckwith–Wiedemann or Silver–Russel syndromes and overexpression of IGF2 is a hallmark of various embryonic tumors, including Wilms tumor." (PMID 39336109, 2024). "Some of the most common genetic alterations of pediatric Wilms tumor include IGF2 overexpression, WT1, and CTNNB1 mutations." (PMID 39234402, 2024). "Lastly, we identified RTL1 as a candidate marker for tumors with unfavorable prognosis due to loss of imprinting of the maternal allele, similar to earlier reports on loss of imprinting of the IGF2 gene in Wilms’ tumors." (PMID 39635126, 2024). "The IC1 (H19 gene) hypermethylation of chromosome 11p15 increases the risk for Wilms tumor due to the biallelic expression of the IGF2 gene." (PMID 37052241, 2023). "Wilms’ tumor is also associated with mutations in the 11p15.5region that affect Igf2 imprinting: altered Igf2expression accounts for nearly 50% of all cases of Wilms’ tumor, and Igf2loss of imprinting is found in the vast majority (90%) of pathological cases." (PMID 33650826, 2021). "Such overexpression can lead to BWSp features; IGF2 overexpression is also seen in 70% of Wilms tumor, explaining the increased predisposition to Wilms tumor in BWSp patients." (PMID 33194904, 2020). "996–1007) show that microRNA processing gene mutations in Wilms tumor lead to an increase in the levels of transcription factor pleomorphic adenoma gene 1 (PLAG1) that in turn activates IGF2 expression." (PMID 30068702, 2018). "Previous studies identified the loss of imprinting at the IGF2 locus as a cause of enhanced IGF2 expression in Wilms’ tumor." (PMID 29707155, 2018). "In the case of the Beckwith-Wiedemann overgrowth syndrome and in Wilms tumor, increased levels of IGF2 have been shown to be causally related to the disease manifestation." (PMID 30068702, 2018). "Note that telomerase expression in bovine adrenocortical cells is correlated with an induction of IGF2 expression, whereas it is associated with a repression of IGF2 expression in immortalized Wilms tumor cells." (PMID 27213811, 2016). "IGF2 upregulation is also known to be associated with an increased risk for embryonal tumors including Wilms tumor." (PMID 25943194, 2015). "Loss of imprinting of IGF-2, first described in Wilms tumor, has since been identified in adult tumors and is associated with an increased risk of colon cancer." (PMID 25424625, 2014). "The upregulation of Igf2 in this Wilms tumor model causes increased signaling through the IGF-IR via pIRS1 and pERK1/2, which drives the proliferation of these abnormal cells." (PMID 22875335, 2013). "For example, loss of methylation of the maternal allele of insulin-like growth factor-II (IGF2) has been associated with increased expression of the growth-promoting gene in Wilms’ tumor." (PMID 23890537, 2013). "For instance, IGF2 imprinting defects have been implicated in Silver-Russell syndrome, Wilms' tumor, hepatoblastoma and ovarian cancer." (PMID 23388414, 2013). "Earlier studies have shown that LOI of IGF2 is associated with somatic overgrowth and embryonal tumors and has been linked to more than 20 types of cancer in humans, including Wilms’ tumor and colorectal, lung, breast and prostate cancer." (PMID 23900345, 2013). "Loss of imprinting was first linked to cancer in 1993, when overexpression to 2-fold of Insulin-like growth factor 2 (Igf2) was identified in Wilms' tumor." (PMID 23110045, 2012). "Hypermethylation at H19 DMR has been associated with a remarkable down-regulation of H19 expression, loss of imprinting of IGF2, and several disorders, including Wilm's tumors in children; a cancer type that is more prevalent in African Americans." (PMID 22414206, 2011).
Wilms tumor (continued). "Loss of heterozygosity of 11p15.5 and loss of imprinting of IGF2 were the most frequent genetic (29%) and epigenetic (40%) alterations in Wilms' tumours, respectively." (PMID 16909133, 2006). "Studies have implicated population differences in the incidence of WT1 mutations, loss of imprinting of the IGF2 locus, and loss of heterozygosity of 1p/16q, or 1q gain as possible bases for epidemiological differences in the disease profile of Wilms tumors in various ethnic groups." (PMID 39272909, 2024). "The reduced incidence of Wilms tumor in the Asian population has been hypothesized to be due to the loss of imprinting (LOI) for the Insulin-like Growth Factor 2 gene (IGF2) occurring at a lower frequency in Asians." (PMID 39272909, 2024). "Prolonged nephrogenesis was observed also in mice with overexpression of Lin28, Lin28b or inactivated Let-7 (Let-7a1; Let-7d; Let-7f1), which also either show direct tumorigenesis or activation of the Igf2 or H19h loci associated with pediatric kidney cancer Wilms' tumor." (PMID 34032268, 2021). "Despite the great potential of modulating microRNA regulation, these models show either direct tumorigenesis or are associated with increased activation of the Igf2/H19 locus, which is the most prominent oncogene in pediatric kidney cancer known as Wilms tumor." (PMID 33672414, 2021). "Perlman syndrome is an autosomal recessive syndrome due to mutation in the gene encoding DIS3L2 exoribonuclease (RNAase); DIS3L2 has been shown to lead to IGF2 overexpression, as seen in the Beckwith–Wiedemann syndrome and is strongly associated with tissue overgrowth and Wilms tumor development." (PMID 33194904, 2020). "At the IGF2/H19 locus, aberrant methylation at DMRs that regulate the expression of IGF2 have been associated with IGF2 deregulation in many cancers, including colorectal, pancreatic and ovarian cancers and Wilms’ tumors." (PMID 23775149, 2014). "Neuroblastoma may also demonstrate 14q allele loss and Wilms' tumour was of interest as epigenetic alterations at the IGF2/H19 locus are common in this tumour." (PMID 15798773, 2005). "In addition, epigenetic alterations at IGF2 and H19 have been implicated in the pathogenesis of sporadic childhood (e.g. Wilms' tumour) and adult (e.g. colorectal) cancers." (PMID 15798773, 2005). "Defects in the imprinting of the IGF2 locus are observed in Beckwith–Wiedemann syndrome, characterized, among other features, by an increased incidence of pediatric malignancies (nephroblastoma or Wilms’ tumor, hepatoblastoma, and rhabdomyosarcoma)." (PMID 38339342, 2024). "Apart from the IGF2 gene, mutations in the WTX and CTNNB1 genes are also known to be implicated in the pathogenesis of Wilms tumors." (PMID 39272909, 2024). "The LOI of the IGF2 gene is known to be the most common epigenetic alteration in Wilms tumors and has been noted in approximately half of all Wilms tumors." (PMID 39272909, 2024). "miR-483-5p, a microRNA (miRNA) overexpressed in primary Wilms’ tumors, has been found to upregulate IGF2 mRNA through enhancement of its transcriptional levels." (PMID 37371750, 2023). "A recent study in Wilms tumor patients’ derived cell lines found IGF2 to be downregulated by miR-155-5p via direct binding to its 3’ untranslated region." (PMID 37371750, 2023). "Histopathology of the mass was consistent with nephroblastoma and immunohistochemistry for anti-insulin-like Growth Factor-2 (IGF-2) antibody revealed immunoreactivity in over 50% of the neoplastic cells." (PMID 37143502, 2023). "It has been known for decades that IGF2 is overexpressed in Wilms’ tumors relative to normal postnatal kidney." (PMID 35741015, 2022). "A loss of heterozygosity (i.e., loss of the maternal allele) or loss of imprinting at the H19/IGF2:IG-DMR (i.e., biallelic expression of IGF2) in Wilms’ tumors was subsequently demonstrated by several teams." (PMID 35741015, 2022).
Wilms tumor (continued). "GATA2 has been reported to directly upregulate IGF2 in chemo-resistant prostate cancer, while IGF2 activity leads to PAX2 overexpression in Wilms’ tumor, suggesting a possible signalling axis in NET-PATZ1." (PMID 34417833, 2021). "In line with this, the majority of Wilms tumour organoids demonstrated high IGF2 gene expression compared with normal kidney, MRTK and RCC organoids." (PMID 32161258, 2020). "A high level of Erk1/2 phosphorylation was also observed in the Wt1-Igf2 Wilms tumor mouse model and was postulated to be due to Igf2 signaling through IGF1R activation." (PMID 33379206, 2020). "Wilms tumour organoids largely retained the high IGF2 expression detected in the parental tumour tissue." (PMID 32161258, 2020). "Wilms tumor rate is more frequent in the H19/IGF2:IG-DMR subgroup than in the cases observed for the UPD." (PMID 33101381, 2020). "The overall tumor risk of H19/IGF2:IG-DMR GOM is ∼23%, specifically with a 21% risk of developing Wilms tumor." (PMID 33101381, 2020). "Patients with H19/IGF2:IG-DMR hypermethylated present Wilms tumor and hepatoblastoma their recurrence is related to IGF2 overexpression during cancer development." (PMID 33101381, 2020). "Igf2 upregulation along with the neighboring gene H19 is particularly interesting as IGF2 is recognized be one of the most important Wilms tumor oncogenes." (PMID 30635573, 2019). "Defects in the imprinting of the IGF2 locus are observed in the Beckwith-Wiedemann syndrome, which increases the incidence of pediatric malignancies as nephroblastoma (Wilms’ tumor), hepatoblastoma, and rhabdomyosarcoma." (PMID 29867024, 2018). "IGF2 LOI occurs in childhood tumors such as Wilms tumor, hepatoblastoma, and rhabdomyosarcoma, as well as in a majority of adult tumors, such as prostate, breast, lung, colorectal, and liver cancer." (PMID 30509319, 2018). "The miR-483 is encoded within an intron of the IGF2 gene, and overexpression of both IGF2 and miR-483 was observed in Wilms’ tumor." (PMID 29401683, 2018). "In cancer, especially in Wilms’ tumor, aberrant methylation of the ICR causes the reactivation of the maternal silent IGF2 allele and the silencing of the active H19 maternal allele." (PMID 29867024, 2018). "For example, promoter methylation has been shown to have an important role in regulation of the IGF2 gene and loci at 11p13 and 11p15 in Wilms tumors." (PMID 21080955, 2010). "Methylation of the DMR0 on the maternal IGF2 allele was inferred using cell lines derived from a BWS patient with paternal uniparental disomy at 11p15.5 loci (UPD) and in Wilms tumour kidney patients with loss of heterozygosity of the maternal allele." (PMID 18365005, 2008). "It has been reported that IGF2 and H19 within the IGF2/H19 domain are expressed abnormally in Wilms' tumours." (PMID 16909133, 2006). "In Wilms' tumours, abnormally high levels of IGF2 mRNA and loss of imprinting (LOI) of IGF2, allowing both paternal and maternal alleles to be transcribed, have been observed." (PMID 16909133, 2006). "Similarly, WT1 typically suppresses IGF2 transcription; thus, WT1 mutations or functional loss led to increased expression of both IGF2 and miR-483, prominently observed in Wilms tumors." (PMID 41463366, 2025). "Notably, analysis of IGF2 expression across more than 1,000 cancer cell lines revealed that IGF2 is selectively and highly expressed in embryonal tumors, including Wilms tumor, hepatoblastoma, rhabdomyosarcoma, CIC–DUX4 sarcoma, and synovial sarcoma." (PMID 40684183, 2025). "In Wilms tumor, miR-155-5p demonstrated an antitumor effect by targeting IGF2." (PMID 39981141, 2025). "Indeed, in Wilms tumors, in which WT1 is biallelically mutated or deleted, Egr1 is upregulated, offering a dual synergistic mechanism for IGF2 increased transcriptional activation." (PMID 37371750, 2023).
Wilms tumor (continued). "For a long time, the only genes known to be mutated or deregulated in Wilms tumors were WT1, IGF2, and genes linked to canonical WNT signaling (CTNNB1, WTX/AMER1), but recent large-scale sequencing projects have greatly extended the number of genes linked to Wilms tumorigenesis." (PMID 33672414, 2021). "Furthermore, loss of heterozygosity or imprinting on chromosome 11p15, which harbors a cluster of imprinted genes, is documented in approximately 70% of Wilms tumors, resulting in biallelic expression of IGF2 and its neighboring H19 gene." (PMID 30635573, 2019). "Furthermore, increased expression of IGF2 through these mechanisms is commonly found as a somatic event in Wilms tumors." (PMID 30068702, 2018). "Thus, augmented IGF2 expression seems to be a common downstream factor in both tissue overgrowth and Wilms tumor through several alternative mechanisms." (PMID 30068702, 2018). "Therefore, we examined the allelic expression of H19 and IGF2, genes known to be aberrantly imprinted in some Wilms tumours." (PMID 29912901, 2018). "In addition to epigenetic alterations, genetic alterations, such as the amplification of paternal alleles leading to overexpression of IGF2 and LOH of the maternal allele leading to reduced expression of H19, were observed in sporadic Wilms’ tumors." (PMID 24373183, 2013). "In this context, whether IGF2 LOI is associated in SFT with global demethylation, as observed in Wilms tumors, warrants methylome analysis of SFT samples." (PMID 23734203, 2013). "In the first report methylation was investigated for the entire IGF2 gene in Wilms tumour samples with and without loss of imprinting." (PMID 18365005, 2008). "In Wilms' tumours, mutation of the Wilms tumour 1 (WT1) gene at the WT1 locus has been reported, and the WT2 locus, comprising the two independent imprinted domains IGF2/H19 and KIP2/LIT1, can undergo maternal deletion or alterations associated with imprinting." (PMID 16909133, 2006). "Our results clearly show that IGF2 LOI occurs in Japanese patients with Wilms' tumour." (PMID 16909133, 2006). "In Wilms tumors, loss of imprinting leads to biallelic expression of IGF2 and reciprocal loss of expression of H19, a non-transcribed RNA with tumor suppressor activities, while IGF2 promotes tumor formation by inhibiting apoptosis." (PMID 16248899, 2005). "Elevated levels of IGF-2 are characteristic for tumours originating from tissues expressing high levels of IGF-2-RNA during foetal life such as nephroblastoma (Wilm's tumour), rhabdomyosarcoma, and HCC as well as in overgrowth disorders such as Beckwith–Wiedemann syndrome." (PMID 12618883, 2003). "However, reminiscent of the situation in Wilms’ tumours, expression of the IGF2 gene on the paternal chromosome can also be disturbed in bladder cancers." (PMID 10944603, 2000). "Such categories include, e.g., the Wilms tumors, in which LOI of IGF2 is a common early initiating event, or the childhood onset retinoblastoma, in which biallelic loss of RB1 is an early causal event." (PMID 40414875, 2025). "miR483, also overexpressed in Wilms tumor and EET MN1-BEND2, enhances transcription of IGF2 and IGF2 antisense (IGF2-AS) genes." (PMID 36604386, 2023). "IGF2 LOI in Wilms tumor and hepatoblastoma is reportedly correlated with hypermethylation of H19-DMR, which is the ICR in the IGF2/H19 domain." (PMID 30509319, 2018). "Work with animal models has provided evidence that increased IGF2 expression is an important contributing factor in both BWS and Wilms tumor." (PMID 30068702, 2018). "In a Wilms tumor cell line, the investigators replicated these findings, in which down-regulation of miR16/34 results in up-regulation of PLAG1, which transactivates Igf2 expression." (PMID 30068702, 2018).
Wilms tumor (continued). "Aberrant expression of imprinted genes, such as those coding for the insulin-like growth factor 2 (IGF2) and neuronatin (NNAT), is a characteristic of a variety of embryonic neoplasms, including Wilms tumor (WT)." (PMID 23825673, 2013). "Another study suggests that nephron progenitors, but not stromal progenitors, give rise to Wilms tumors in mouse models with β-Catenin activation or Wt1 ablation and Igf2 upregulation." (PMID 40087269, 2025). "Within the PPTP/C in vivo models, rhabdomyosarcoma and Wilms tumor models consistently show very high levels of IGF2 expression and low levels of IGF1 expression, while IGF2 expression is lower and more variable for neuroblastoma and osteosarcoma models and is lower still for Ewing sarcoma." (PMID 39510293, 2024). "Wilms tumor represents the most common cancer in BWS patients with a high prevalence in combination with telomeric defects in H19/IGF2:IG-DMR -GOM and UPD subgroups (21.1% vs. 6.2%, respectively, P < 0.001); subjects with centromeric defects display a lower rate." (PMID 33101381, 2020). "In the human WT1 mutant Wilms tumor cells we did not observe a phosphorylation of this receptor in the proteome studies, although IGF2 RNA expression was high." (PMID 33379206, 2020). "In Wilms’ tumors, reduced expression of lncRNA KCNQ1DN existing far from the H19/IGF2 region and may play regulatory role in tumor progression." (PMID 31001325, 2019). "H19-DMR hypermethylation leads to IGF2 LOI and H19 silencing in Wilms tumor and hepatoblastoma." (PMID 30509319, 2018). "A recent study claims that loss of imprinting (LOI) of IGF-2 gene defines a molecular subgroup of Wilms tumors that have a different pathologic subtype, a later age of onset, and greater IGF-2 expression than those without LOI." (PMID 22662119, 2012). "The lack of therapeutic efficacy of U0126 in this Wilms tumor model and only a transient decrease of glucolytic activity could be explained, at least in part, by continuing IGF2-induced signaling from IGF1R through the PI3K-AKT-mTOR pathway, bypassing the block in MAPK signaling." (PMID 22875335, 2013). "In a study of 70 BWS and 2 SRS patients, the methylation patterns at the IGF2 DMR0 resembled that at the H19 DMR, in contrast to 33 non-syndromic Wilms tumours in which IGF2 DMR0 methylation was negatively correlated with H19 DMR methylation." (PMID 22646060, 2012).